CXCL10 (C-X-C motif chemokine ligand 10)
Diseases named in the same sentence as CXCL10 in open-access papers (continued):
Sharing a sentence is not in itself a finding about the gene and the disease.
atherosclerosis (continued). "Genetic inactivation of Cxcr3 or its ligand Cxcl10, that were both detected in mouse lesions in the ApoE−/− strain, resulted in decreased atherosclerosis burden that was accompanied by a decrease in inflammatory CD4+ T cell content, an elevated number of Tregs, and increased expression of IL-10." (PMID 24741577, 2014). "The role of CXCL10 in atherosclerosis has been studied in the past." (PMID 24868552, 2014). "Thus, IFN-γ/CXCL10 axis may provide novel strategies to promote endothelial healing and prevent further atherosclerosis complications after therapeutic interventions." (PMID 31824304, 2019). "On the other hand, IFN-γ inducible protein, CXCL10/IP-10, a member of the chemokine family with pro-inflammatory and anti-angiogenic properties, has been proposed as a key link between inflammation and angiogenesis, lending credence to its role in inducing atherosclerosis." (PMID 25092442, 2014). "Because macrophage foam cells are characteristic of atherosclerosis, we measured both plaque lipid (31.3 ± 8.0% treated versus 29.5 ± 7.0% control) and macrophage content (31.7 ± 7.6% treated versus 27.8 ± 7.0 control), where both remained unchanged upon CXCL10 inhibition." (PMID 22164344, 2011). "These literatures demonstrate that both CXCL10 and CCL5 play critical roles in atherosclerosis development, and their inhibition is an effective anti-atherogenic approach." (PMID 36247423, 2022). "For example, the high expression of C-X-C motif chemokine ligand 10 (CXCL10), a chemokine that extensively contributes to atherosclerosis and coronary artery disease in endothelial cells, is driven in part by PRMT5 methylation of NF-κB at R30 and R35." (PMID 34685445, 2021). "The role of CXCL10 in CVD has been extensively described, for example for atherosclerosis, aneurysm formation, and myocardial infarction." (PMID 24868552, 2014). "The upregulation of key proteins such as IL-6, CXCL10, and CCL19 suggests an inflammatory signature in OBO individuals that may promote atherosclerosis along with other upregulated pro-inflammatory cytokines activating monocytes." (PMID 40076884, 2025). "CXCL10, a member of the CXC family of chemokines, has diverse biological functions in different cell types, thus contributing to the initiation and progression of atherosclerosis." (PMID 37189834, 2023). "CXCL10 and CLL5 protein levels were also increased in the HCAECs-derived secretome, which could aggravate the progression of atherosclerosis by promoting the proliferation and atherogenic phenotype switching of VSMCs." (PMID 36497143, 2022). "These genes included the chemokines CCL5, CXCL10, CCL8, CXCL9, CCRL2, which were also up-regulated in carotid or coronary human plaques, as shown here, and together reflect pro-atherogenic responses in human atherosclerosis." (PMID 25196434, 2014). "In human atherosclerosis, but not in healthy arteries, endothelial cells, smooth muscle cells, and macrophages express CXCL10." (PMID 22164344, 2011). "In addition, various immune-related genes have been examined in an atherosclerosis animal model, and genes such as CXCR6, CXCL10, CXCR3 and CXCL16/scavenger receptor have been shown to be involved in the progression of atherosclerosis in animal models." (PMID 18673543, 2008). "In addition, apolipoprotein E (APOE)/Cxcl10/mice fed with a Western-style diet for either 6 or 12 weeks demonstrated a significant atherogenesis inhibition compared with APOE (−/−) controls, revealing the role of CXCL10 in atherosclerosis progression." (PMID 34835155, 2021). "In this study, we discovered the overexpression of lnc-SLC15A1-1 activation in HUVECs treated with HG + IS and the subsequent upregulation of CXCL10 and CXCL8 genes and proteins, which might explain the connection between endothelial injury and atherosclerosis." (PMID 34941711, 2021).
atherosclerosis (continued). "Furthermore, the systemic concentration of chemokines like GRO-α, MCP-1, and IP-10 (CXCL10) shown to contribute positively to the initiation and progression of atherosclerosis were increased systemically in Apoe−/−Peli1−/− mice versus Apoe−/− mice in advanced atherosclerosis." (PMID 35805095, 2022). "However, higher protein levels of CXCL10 as well as CXCL11 were detected in human and carotid atherosclerotic tissues whereas none of them were detected in normal vessel walls, highlighting that both proteins are playing an important role in the development of atherosclerosis." (PMID 26663990, 2015).
multiple sclerosis (65 papers, 2009 to 2026). A progressive autoimmune disorder affecting the central nervous system resulting in demyelination. "CXCL10 has also been implicated in numerous neuropathologies, including those involved in abnormal α-syn deposition, such as PD, multiple sclerosis, and human immunodeficiency virus (HIV) dementia." (PMID 31906130, 2019). "CXCL10 overexpression was demonstrated to be mediated also by rs3921-derived allele in patients affected by multiple sclerosis, invasive asperigillosis, and hematological malignancies." (PMID 27551316, 2016). "The overexpression of CXCL10 or interferon gamma-induced protein 10 (IP-10) has been observed in several neurodegenerative diseases including multiple sclerosis (MS), Parkinson's disease (PD) HIV-associated dementia, and Alzheimer's disease (AD)." (PMID 23997430, 2013). "Moreover, raised serum CXCL10 levels can be associated with a worse outcome after experiencing intracerebral haemorrhage, and an elevated CXCL10 level in the CSF has been acknowledged as a biomarker of active multiple sclerosis." (PMID 37765263, 2023). "Investigation into the contribution of CXCL10 in neurological disease has identified elevated levels of CXCL10 to be present in multiple sclerosis, Alzheimer's disease, and cerebral malaria." (PMID 40522207, 2025). "For example, biologics targeting CXCL10 are currently being evaluated for treatment of inflammatory bowel disease and multiple sclerosis." (PMID 38317183, 2024). "Several lines of evidence indicated microglia/macrophages as a source of CXCL10 during multiple sclerosis and CNS viral infections." (PMID 36890539, 2023). "CXCL10 is a multiple sclerosis (MS)-relevant chemokine that is present in the injured central nervous system and recruits CXCR3+ immune cells toward injured tissues." (PMID 37627269, 2023). "CCL3, IL-12B, CXCL10 and IL-8 discriminated between multiple sclerosis patients and controls, but only IL-12B differed between patients with relapsing-remitting and progressive multiple sclerosis." (PMID 36756308, 2023). "CXCL10 is induced locally in the CNS in diverse pathologic states, e.g., Alzheimer’s disease and multiple sclerosis (MS)." (PMID 35892669, 2022). "CXCL10 is also strongly upregulated in many other autoimmune and inflammatory diseases like multiple sclerosis and allograft rejection, resulting in the accumulation of CXCR3+ T cells." (PMID 34481469, 2021). "In patients with multiple sclerosis, the concentration of CXCL10 and CCL2 in CSF correlates with disease activity, returning to normal levels upon therapy." (PMID 34764955, 2021). "CXCL10 is emerging as a key inflammatory molecule expressed during neuroinflammatory processes such as autoimmune disorders (e.g., multiple sclerosis or encephalitis)." (PMID 32753493, 2020). "CXCL10, a chemokine elevated in various central nervous system (CNS) pathologies like Alzheimer's disease, multiple sclerosis, and Rasmussen encephalitis, has been shown to elicit elevated neuronal excitability after acute and chronic exposure." (PMID 33312155, 2020). "CXCL10 signaling is important in other brain pathologies, including Alzheimer’s disease and multiple sclerosis." (PMID 23078780, 2012). "The involvement of this chemokine in different CNS disorders has been demonstrated, such as viral meningitis and multiple sclerosis, where increased CXCL10 levels in the CSF correlated with tissue infiltration of T lymphocytes." (PMID 19554086, 2009). "High levels of CXCL10 were found in the cerebrospinal fluid of multiple sclerosis patients' during intense inflammatory process." (PMID 19473542, 2009). "Moreover, in multiple sclerosis, CXCL10 is thought to have a pro-inflammatory impact affecting the Th1 subset of CD4-positive T helper cells, thereby influencing disease evolvement." (PMID 39436967, 2025).
multiple sclerosis (continued). "Endothelial cells can secrete CXCL10, contributing to the progression of disorders such as retinal ischemia‒reperfusion, Alzheimer's disease, multiple sclerosis, and neuronal injury; it binds to the CXCR3 receptor and can regulate the immune response by activating and attracting leukocytes." (PMID 40128669, 2025). "Epstein–Barr virus (EBV) infection and various chemokines, including CCL20, CXCL8 and CXCL10 are considered to participate in the pathogenesis of multiple sclerosis (MS), and several studies point to a direct regulatory effect of EBV on the expression of these chemokines." (PMID 39125633, 2024). "Additionally, increased levels of CXCL10 correlated with markers of intrathecal inflammation were found in CSF of patients with multiple sclerosis (MS), while CCL2 was suppressed." (PMID 38931342, 2024). "In contrast to previous studies that identified microglia/macrophages as the primary sources of CXCL10 in multiple sclerosis patients, we detect evident CXCL10 expression primarily in ECs, but not in VDR-deficient microglia/macrophages in the ischemic brain." (PMID 36890539, 2023). "Therefore, the adverse effect of CXCL10/IP-10 on oligodendrocyte progenitor cells appears to occur in patients with multiple sclerosis." (PMID 35457023, 2022). "Interestingly, we found that upon direct contact with Th17-polarized cells, OLs significantly upregulate their expression of chemokines CXCL10 and CXCL11, whose levels in the CSF are associated with clinical evolution in multiple sclerosis." (PMID 35479072, 2022). "IFN-γ and CXCL10/IP-10 are elevated in the cerebrospinal fluid of patients with multiple sclerosis." (PMID 35457023, 2022). "CXCL10 could promote the invasion of lymphocytes and macrophages, affect myelination in a viral model of multiple sclerosis, and induce neuropathic pain in DRGs after chronic constriction injury." (PMID 33225981, 2020). "This CXCL10/11/9 chemokine gene expression signature also accounted for the identification of “pathogenesis of multiple sclerosis” as the top disease-related canonical pathway identified using IPA, consistent with a proinflammatory response contributing to disease pathology in active VL." (PMID 31419223, 2019). "They found the combination of chitinase-3-like-1, CXCL10, CXCL12, CXCL13 increased the AUC for predicting conversion to clinically definite multiple sclerosis after first attack above any single biomarker in isolation." (PMID 38368354, 2024). "CXCR3 is abundantly expressed on CNS-infiltrating T cells in multiple sclerosis patients and coordinates CNS-directed T cell migration in response to its three ligands, CXCL9/CXCL10/CXCL11." (PMID 38349430, 2024). "Through sophisticated analyses, we identified four cytokines with limited association with each other, that discriminated between patients with multiple sclerosis and healthy controls, namely, CCL3, IL-12B, CXCL10 and IL-8." (PMID 36756308, 2023). "In experimental multiple sclerosis mouse model, gal3−/− mice infected with Theiler’s murine encephalomyelitis virus have reduced CCL2, CCL5, CCL8, and CXCL10 expression and lower number of infiltrating cells in the brain subventricular zone." (PMID 28217127, 2017). "For instance, astroglial chemokines have an influence upon microglia/macrophage activation in multiple sclerosis with CCL2 (MCP-1) and CXCL10 (IP-10) directing reactive gliosis." (PMID 25977914, 2015). "CXCL10 and its receptor CXCR3 play a critical role in multiple sclerosis, particularly in leukocyte recruitment into the CNS." (PMID 20186338, 2010). "Recent evidence has also indicated that serum expression of CXCL10 and CXCL11 is increased in multiple sclerosis patients and may be involved in disease pathogenesis." (PMID 33806460, 2021).
multiple sclerosis (continued). "Moreover, other groups also described elevated levels of IL-1β or IL-1β/TNF-α induced molecules like IL-1ra, IL-6, IL-8, IL-13, G-CSF, and Cxcl10 (IP-10) in the CSF of NMO patients, compared to the CSF of patients with multiple sclerosis or other neurological diseases." (PMID 24252536, 2013). "CCR5 is commonly expressed by intrathecal Th lymphocytes in both infectious (neuroborreliosis) and non-infectious (multiple sclerosis, MS) cns inflammation, usually alongside CXCR3 receptor for chemokines CXCL9 and CXCL10, but its role remains debatable." (PMID 26906062, 2016).
liver fibrosis (64 papers, 2011 to 2025). "CXCL10-deficient mice exhibited less CCl4-induced liver fibrosis than wild-type mice and a neutralizing anti-CXCL10 antibody significantly inhibited hepatic fibrosis." (PMID 35432206, 2022). "Liver fibrosis (measured by both transient elastography and liver biopsy) was statistically significantly associated with intrahepatic mRNA for CXCL10 and CXCR3 using linear and logistic regression analyses adjusted for CD4 T-cell count." (PMID 32898182, 2020). "In CXCL10 deficient mice, an increase in liver fibrosis is seen due to inhibition of natural killer cells (NK) which target hepatic stellar cells." (PMID 24736562, 2014). "Studies have shown that peripheral levels of CXCR3-associated chemokines, particularly CXCL10, are significantly associated with liver fibrosis in chronic HCV-infected patients." (PMID 24516541, 2014). "Blockage or deficience of CXCL10 leads to the reduced liver fibrosis in CCL4 induced liver fibrosis model." (PMID 22905138, 2012). "CXCR3 associated chemokines CXCL9 and CXCL10 were reported to be in correlation with liver fibrosis, but their roles in liver subpopulations of mice with schistosomiasis were not clear." (PMID 22905138, 2012). "Interestingly, CXCL10 was reported to be associated with liver fibrosis in individuals co-infected with HIV and Epstein–Barr virus (EBV)." (PMID 37656815, 2023). "HCV-induced CXCL10 has been shown to increase hepatocyte turnover, resulting in the development of fibrosis and cirrhosis and has also been implicated as a positive predictor of liver fibrosis recurrence in HCV-infected liver transplant patients." (PMID 36358697, 2022). "Of interest, chemokine genes, such as CCL5, CCL2 and CXCL10, could activate human hepatic stellate cells, which are associated with hepatic fibrosis, and CXCL10 is an important gene for the treatment response of interferon treatment." (PMID 26133378, 2015). "Similarly, CXCL10-deficient mice showed massively reduced liver fibrosis upon carbon tetrachloride administration by inducing the inactivation of HSCs by NK cells." (PMID 24646914, 2014). "Of note, recent data indicate that the chemokines receptor CXCR3 and its ligands, especially CXCL10 (IP-10) may play an important role in the regulation of HCV-associated liver fibrosis by yet incompletely understood mechanisms." (PMID 22792160, 2012). "A strong association between CXCR3-associated chemokines CXCL9 and CXCL10 with liver fibrosis suggested that they may have promise as new non-invasive markers of liver fibrosis in HCV infected patients." (PMID 21299910, 2011). "CXCL10 promoted liver fibrosis by preventing NK cell-mediated inactivation of hepatic stellate cells." (PMID 41343465, 2025). "A total of 15,010 study subjects were enrolled, and 11,509 study subjects (mean age 54.0 ± 11.1 years, 48.7% men) were included; CXCL10 was found to be the inflammatory nexus between liver fibrosis and prevalent AF using a multivariate linear regression model." (PMID 40264510, 2025). "Using large-scale targeted proteomics, we found that CXCL10 is related to both liver fibrosis, as defined by the fibrosis-4 index, and to atrial fibrillation." (PMID 39380717, 2024). "In the case of CXCL10, the important information from the point of view of this work is that it promotes liver fibrosis by preventing NK cell-mediated inactivation of hepatic stellate cells." (PMID 37893992, 2023). "The anti-CXCL10 antibody can reduce lipid accumulation and infiltration of inflammatory cells, consequently preventing steatohepatitis and reducing hepatic fibrosis." (PMID 36457551, 2022). "In CCl4 or FFC-induced liver injury and liver fibrosis, CXCL10 can promote liver fibrosis and infiltration of inflammatory macrophages." (PMID 35484116, 2022). "In chronic HCV infection, CXCL10 contributed to the development of necroinflammation and liver fibrosis." (PMID 36366543, 2022).